TNF (tumor necrosis factor)
Diseases named in the same sentence as TNF in open-access papers (continued):
Sharing a sentence is not in itself a finding about the gene and the disease.
atherosclerosis (continued). "Naringenin can directly or indirectly regulate cytokines such as TNF-α, IL-6, IFN-γ, and signalling pathways NF-kappa B and MAPK and has a relieving effect on atherosclerosis." (PMID 35845584, 2022). "TMAO increases the expression of IL-6 and tumor necrosis factor (TNF) in macrophages, which further promotes a proinflammatory environment and atherosclerosis plaque formation." (PMID 35880171, 2022). "HMOX1 has been shown to reduce atherosclerosis in mouse models, and upregulation of Nrf2/HMOX1 protected the human endothelial cells against TNF-α activation." (PMID 36359349, 2022). "In the development of atherosclerosis, HMGB1 mediates the expression of proinflammatory mediators of endothelial cells during the initial stage of plaque formation, including TNF-α, IL-8, MCP-1, adhesion molecules (ICAM-1, VCAM-1), MIP-1α, and MIP-1β." (PMID 36176426, 2022). "A higher TNF-α/adiponectin ratio in HCV-infected subjects is shown to be correlated with the development of IR and atherosclerosis." (PMID 36059478, 2022). "Similar to the pathological process of atherosclerosis, the initiation phase of CAVD involves chemotactic action mediated by cytokines such as TNFα, IL-1β, and IL-6 to activate and recruit immune cells to valve tissue." (PMID 36589450, 2022). "Pathological tests (oil red O, HE, and Masson staining) combined with biochemical indices (TC, TG, LDL-C, HDL-C, TNF-α, hs-CRP, NO, SOD, MDA, CAT, and GSH-Px) were performed to evaluate the pathological degree of atherosclerosis in each group." (PMID 36180828, 2022). "Glycosylated apo A-IV induces pro-inflammatory response in vitro and increases the expression of tumor necrosis factor (TNF) -α and adhesion molecules by the nuclear receptor NR4A3, thereby promoting atherosclerosis in apo E-/- mice." (PMID 36072863, 2022). "Endothelial barrier integrity is compromised in the process of atherosclerosis, and selective inhibition of HDAC6 in human pulmonary artery ECs has been shown to prevent TNF-α–induced EC barrier dysfunction and endotoxin-induced pulmonary edema." (PMID 34220539, 2021). "Both TNF-α and IFN-γ resulted in the remarkably increased accumulation of subintimal macrophages and accelerated atherosclerosis." (PMID 34566648, 2021). "Macrophage-derived IL-12 and IL-18 induce Th1 cell differentiation, responding to oxLDL stimuli by secreting further TNF-α and interferon γ (IFN-γ), a powerful inductor of atherosclerosis at the different stages of the process." (PMID 35008500, 2021). "The increased expression levels of MCP-1 and TNF-α in transplanted PVAT tissue can aggravate endothelial dysfunction and atherosclerosis in distant vessels by enhancing the inflammatory response." (PMID 34456867, 2021). "Through this network pharmacology study, we found that peach kernel-safflower in treating DN mainly involves the AGE-RAGE signaling pathway in diabetic complications, fluid shear stress and atherosclerosis, IL-17, HIF-1, and TNF signaling pathways." (PMID 33604381, 2021). "A total of 160 KEGG pathways (P < .05), including fluid shear stress and atherosclerosis, the AGE-RAGE signaling pathway in diabetic compositions, the TNF signaling pathway, and the IL-17 signaling pathway were identified." (PMID 34889224, 2021). "Several inflammatory and atherosclerosis-related stimuli have been shown to induce OLR1 expression, including lipopolysaccharide (LPS), TNFα, interleukin-1 (IL-1), interferon gamma (IFNγ), oxLDL, and angiotensin II." (PMID 34867460, 2021). "The top 10 significantly enriched pathways contained pathways in cancer, lipid and atherosclerosis, fluid shear stress and atherosclerosis, AGE-RAGE pathways, TNF pathways, IL-17 pathways, and microbial infection-related pathways." (PMID 34970312, 2021). "The results showed that the KEGG pathways in which AKT1 was involved included the TNF signaling pathway, MAPK signaling pathway, human cytomegalovirus infection, fluid shear stress and atherosclerosis, and hepatitis C." (PMID 34077310, 2021).
atherosclerosis (continued). "Several signaling pathways including TNF and cytokine–cytokine receptor interaction, fructose and mannose metabolism and HIF-1, hematopoietic cell lineage and fluid shear stress, and atherosclerosis and estrogen were selected." (PMID 34336943, 2021). "Since migration, proliferation, and phenotypic modulation of VSMCs are the critical factors contributing to the progression of atherosclerosis, we first examined the effects of PPP and PU on TNF-α-induced migration of VSMCs using the wound-healing assay." (PMID 34262908, 2021). "The aim of this research was to assess the effect of Avn C on expression of MMP-9 on TNF-α-activated human arterial smooth-muscle cells (HASMC) and signaling involved in its anti-atherosclerosis activity." (PMID 33841150, 2021). "M1 macrophages are mostly abundant in unstable plaques and promote atherosclerosis progression by secreting pro-inflammatory cytokines MCP-1 and TNFα." (PMID 35046806, 2021). "This is in line with the use of APN treatment in atherosclerosis; pretreatment with APN reduces LPS-stimulated TNF-α production and stimulates production of IL-10 in human and pig macrophages." (PMID 33616153, 2021). "Furin activates many pro-inflammatory cytokines, such as TNF-α and IFN-γ, which leads to the progression of atherosclerosis." (PMID 34579647, 2021). "As the main transcription factor of the inflammatory response, NF-кB can be activated by IL-6, TNF-α, CRP, and so on, which participates in the whole process of atherosclerosis." (PMID 34568579, 2021). "In our study, the mRNA levels of TNF-α and IFN-γ were abundantly expressed in the atherosclerotic lesions of the aorta in atherosclerosis mice, while the levels of IL-10 were the opposite." (PMID 34566648, 2021). "KEGG pathway analysis revealed that the immune-related DEGs mainly involved cytokine–cytokine receptor interaction, prostate cancer, TNF signaling pathway, MAPK signaling pathway, fluid shear stress and atherosclerosis, and inflammatory bowel disease." (PMID 34956318, 2021). "We previously reported that BAIBA reduces tumor necrosis factor (TNF)-α-induced expression of vascular cell adhesion molecule (VCAM)-1 in human umbilical endothelial cells, suggesting that BAIBA acts to prevent atherosclerosis by physical training." (PMID 31963899, 2020). "Of the many chemokines and cytokines that exist, five (IL-1, IL-6, TNF-α, IL-8, and CCL2/MCP-1) are involved in diseases such as psoriasis, rheumatoid arthritis, and atherosclerosis." (PMID 34211530, 2020). "Th1 cells play an important role in the development of atherosclerosis by secretion of inflammatory cytokines such as IFN‐γ, IL‐2, TNFα/β and M1 macrophages stimulation." (PMID 33230950, 2020). "Several inflammatory cytokines, such as interleukin-1β (IL-1β) and tumor necrosis factor-α (TNF-α), involved in the pro-inflammatory signaling in the atherosclerosis progression." (PMID 32472055, 2020). "Administration of AST-120 reduced the severity of atherosclerosis through suppression of the TGF-β and TNF-α pathway." (PMID 32276394, 2020). "Up-regulation of miR-9 reduced aortic plaque area, the proliferation of collagen fibers, Mac-3-labeled macrophages and levels of IL-6, IL-1β, and TNF-α by suppressing SDC2 and the FAK/ERK signaling pathway, thereby ameliorating atherosclerosis in ACS mice." (PMID 32765295, 2020). "Among the hub genes, TNF, PTPRC (also known as CD45), VCAM1, CD86 and MMP9 have been confirmed as inflammatory biomarkers of atherosclerosis." (PMID 32213192, 2020). "Some inflammatory factors such as TNF-α can promote the expression of CD47 and accelerate the progression of atherosclerosis and plaque formation." (PMID 32733941, 2020). "The participation of inflammatory cytokines such as tumor necrosis factor (TNF), interleukin (IL)-1b, and IFN-γ at all stages of atherosclerosis is confirmed in some experimental works." (PMID 32676207, 2020).
atherosclerosis (continued). "SCFA can inhibit NF-κB and tumor necrosis factor (TNF) signaling pathway, resulting in the decrease of expression of VCAM-1 and ICAM-1, thus inhibiting the development of atherosclerosis." (PMID 32002588, 2020). "Various stressful conditions such as hypoxia or tumor necrosis factor alpha (TNF-α), both simulating an inflammatory environment as observed in atherosclerosis, affected the proteome and transcriptome of EVs secreted by cultured ECs." (PMID 32523544, 2020). "Cytokine IL-6, TNF-α, and MCP-1 promote atherosclerosis and are classified as pro- cytokines, while cytokine IL-10 and TGF-β suppress the formation and progression of atherosclerosis and are categorized as anti-atherogenic cytokines." (PMID 32611832, 2020). "Genetic depletion of NEXN-AS1 dramatically increased atherosclerosis in ApoE–/– mice, with concurrent increases in markers of vascular inflammation such as VCAM-1, ICAM-1, TNF-α, and MCP-1." (PMID 33021969, 2020). "Previous studies in HFD-induced atherosclerosis mice reported that BBR administration remarkably reduced the mRNA expression of pro-inflammatory cytokines, including TNF-α, IL-1β, and IL-6, in ileal and carotid arteries." (PMID 32231564, 2020). "Previous studies have reported that the protein expressions of MCP-1, TNF, and AT1R are elevated and play a significant role in atherosclerosis." (PMID 32258142, 2020). "While MAARS expression is increased with progression of atherosclerosis and decreased with regression in aortic macrophages, MAARS expression also decreased in BMDMs treated with TNF-α and CPT." (PMID 33262333, 2020). "Cytokines secreted by T cells, such as γ-interferon and TNF-α, stimulate macrophage activation, ox-LDL uptake, and vascular smooth muscle cell (SMCs) migration, promoting atherosclerosis and reducing plaque stability." (PMID 32733941, 2020). "In a previous study, we found that the ablation of galectin-12 decreased the secretion of MCP-1, TNF-α, and IL-6 in lipopolysaccharide (LPS)—and saturated fatty-acid-stimulated macrophages, suggesting that galectin-12 may potentially play a role in the pathogenesis of atherosclerosis." (PMID 32752134, 2020). "Here, we found that compared with the Control group mice, serum levels of TNF-α, IL-1β, IL-6 were significantly increased, and IL-10 and ADPN levels were significantly decreased in HFD-induced atherosclerosis mice (Model group; all p < 0.001)." (PMID 32231564, 2020). "The vicious cycle created between OxLDL macrophage activation, TNF-α and IL-6 macrophage secretion, and MCP-1-macrophage recruitment greatly boosts the development of atherosclerosis." (PMID 32752134, 2020). "In addition, atherosclerosis is considered to be a chronic inflammatory disease of the large and medium arteries, with changes in pro-inflammatory cytokines such as tumor necrosis factor-alpha (TNF-α),interleukin (IL)-6, and IL-1β, and anti-inflammatory cytokines including IL-10." (PMID 32231564, 2020). "In this case, inflammatory cells and activated endothelial cells in atherosclerotic plaques upregulate adhesion molecules and release inflammatory cytokines such as tumor necrosis factor-α (TNF-α), IL-6, and IL-1β, promoting the progression of atherosclerosis." (PMID 33330454, 2020). "This is achieved by releasing chemokines and cytokines that include IL-1, IL-6, TNF-α, IFN-γ, and, by producing ROS, growth factor and VSM cell proliferation, thus accelerating the development of atherosclerosis." (PMID 31354915, 2019). "Another study that used a low dose of rivaroxaban (28.5 ng/mL in plasma) was able to attenuate progression of atherosclerosis by roughly 25%, as well as reduced inflammation, as reflected by decreased IL-1β, MCP-1, and TNF-α mRNA and protein levels." (PMID 30846818, 2019).
atherosclerosis (continued). "The induction of p16Ink4a and TNFα-mediated chronic inflammation and oxidative stress suggests that these factors may be involved in the mechanism of the loss of embryonic progenitor cell (EPC) proliferative capacity and their increased vulnerability to aging and atherosclerosis." (PMID 31689891, 2019). "Recent studies have indicated that TNFα activation of the p38 MAPK→p16Ink4a promotes the senescence of endothelial progenitor cells and demonstrates their vulnerability to atherosclerosis." (PMID 31689891, 2019). "Inflammation in atherosclerosis is orchestrated by cytokines and IFN-γ, IL-1β and TNF-α represent three major pro-atherogenic cytokines." (PMID 31202985, 2019). "Among them, interleukin 1β (IL-1β), tumor necrosis factor α (TNF-α), IL-6, and monocyte chemokine protein 1 (MCP-1) are highly secreted and play major roles in atherosclerosis, VSMC dysfunctions, and inflammation of the arterial wall." (PMID 31824304, 2019). "Under these conditions, the adipose tissue produces proinflammatory adipokines, such as tumor necrosis factor-alpha (TNF-α), interleukin (IL)-6, monocyte chemoattractant protein-1 (MCP-1), lipocalin-2, and resistin, which induce atherosclerosis." (PMID 30857216, 2019). "Macrophage-derived IL-12 and IL-18 induce Th1 cell differentiation, responding to oxLDL stimuli by secreting further tumour necrosis factor α (TNF-α) and interferon γ (IFN-γ), a powerful inductor of atherosclerosis at the different stages of the process." (PMID 31354915, 2019). "T-helper-1 (Th-1) lymphocytes secrete pro-inflammatory cytokines, such as interferon-gamma (IFN-γ), IL-2 and TNF-α, which activate macrophages, endothelial cells and SMC, therefore propagating and accelerating atherosclerosis." (PMID 31357404, 2019). "Ox-LDL stimulates macrophages to release pro-inflammatory cytokines, such as interleukin (IL)-1β and tumor necrosis factor-α (TNF-α) to trigger pro-inflammatory and pro-oxidant events in the initiation, propagation, and activation of atherosclerosis." (PMID 31214032, 2019). "Blood levels of cytokines IL-17, IFN-γ, TNF-α, the macrophage inflammatory protein (MIP)-1α and MIP-1β, the chemotactic protein MCP-1 and the growth factor VEGF were elevated in cases with atherosclerosis versus controls." (PMID 31821324, 2019). "By the administration of probiotic VSL#3, interesting modulations on host metabolism have been described, such as the modest reduction of IL1, TNF-α, and IL6, the main responsible cytokines of the inflammatory atherosclerosis." (PMID 31205450, 2019). "Our previous study indicated that PDS exhibit more potent effects on the inhibition of vascular inflammation induced by tumor necrosis factor α (TNF-α) in vitro, suggesting the better efficacy in anti-atherosclerosis, compared to the PTS." (PMID 31623159, 2019). "In this report, we decided to focus on PTP1B-mediated cytokine attenuation as seen with IL-8, given its importance in atherosclerosis, leaving the study of PTP1B-mediated cytokine increase (TNFα and TGFß) for a subsequent study." (PMID 30832675, 2019). "Inflammatory cytokines, including tumor necrosis factor alpha (TNF-α), interleukin (IL) 1α (IL1α), IL1ß, IL-2, IL6 and IL8 are involved in the pathogenesis of atherosclerosis, participating in all stages of this condition." (PMID 30479572, 2018). "Lipopolysaccharide (LPS)-induced monocytes activation such as THP-1 macrophage system promoted expression of proinflammatory genes TNF-alpha and Cox-2 dependent of angiotensin type 1 receptor (AT1R) has essential action in the pathogenesis of atherosclerosis." (PMID 30410927, 2018). "Tumor necrosis factor-α (TNF-α) is expressed by myocardial cells under stress and it is a harmful cardiokine involved in atherosclerosis." (PMID 29744364, 2018). "Pro-inflammatory cytokines, such as IL-1, TNF-α, C-reactive protein (CRP), IL-2, and IL-6, all increase in patients with atherosclerosis." (PMID 30386532, 2018).
atherosclerosis (continued). "Increased levels of various inflammatory factors in the circulation that play a critical role in the pathogenesis of atherosclerosis, including IL-1β, IL-6, MCP-1 and TNF-α, were detected." (PMID 30413028, 2018). "The present study revealed that the secretion of inflammatory factors (TNF-α and IL-1β) and chemotactic factor (MCP-1) by macrophages was driven by NF-κB, contributing to more severe inflammatory and autoimmune reaction in atherosclerosis progression." (PMID 30314997, 2018). "Inflammatory mediators, such as RCP, TNF-α, IL-6, IL-18, and CD40L, are involved in the pathogenesis of inflammation and atherosclerosis." (PMID 29849875, 2018). "Several cytokines and chemokines, such as tumor necrosis factor-alpha (TNF-α), interleukin-1β (IL-1β), interleukin-6 (IL-6), and monocyte chemoattractant protein-1 (MCP-1), are important contributors in atherogenesis and atherosclerosis." (PMID 29118465, 2017). "The interaction between TNF-α 1031T/C and HTLV-I for atherosclerosis-related disease incidence was statistically significant (p = 0.020)." (PMID 28576445, 2017). "Given that oxLDL plays a key role in all stages of atherosclerosis by regulating the expression of JAB1 and pro-inflammatory cytokines, we showed an oxLDL-induced upregulation of TNF-α and IL-6 mRNA expression and protein secretion in differentiated human MФ." (PMID 28173800, 2017). "Our findings also show that BMP9 and BMP10 synergize with TNFα to induce expression of BMP2, which is a known regulator of endothelial inflammation and plays a role in atherosclerosis." (PMID 28646109, 2017). "ATK2, IKBKB, RAF1, CHUK, TNF, JUN, and PRKCA were mainly involved in fluid shear stress and the atherosclerosis pathways, pathways in cancer, and the PI3K-Akt signaling pathway." (PMID 29177114, 2017). "The targets of ATK2, IKBKB, RAF1, CHUK, TNF, JUN, and PRKCA were mainly involved in fluid shear stress and the atherosclerosis and PI3K-Akt signaling pathways." (PMID 29177114, 2017). "The involvement of common pro-inflammatory cytokines, such as interleukin - 1 and 6, tumor necrosis factor-alpha (TNF-α), play a role in the development and progression of both RA and atherosclerosis." (PMID 28367205, 2017). "As monocyte pass through the endothelial layer and differentiate, they produce various bioactive factors such as TNF-α, interleukins, MCP 1 etc., which promote inflammation in atherosclerosis." (PMID 27809851, 2016). "It is generally accepted that TNF-α and IL-6 have important role in pathogenesis of T2DM and also atherosclerosis." (PMID 28033351, 2016). "Several cytokines (e.g. IL1β, IL6, and TNFα) are known to stimulate the expression of ICAM-1 and VCAM-1, two important molecules involved in the development of atherosclerosis." (PMID 27277003, 2016). "Herein, we have shown that MED can significantly inhibit the ox-LDL-induced expression of TNF-α, IL-6, and IL-1β both in RAW264.7 cells and in plaque lesion areas, which suggests that MED can suppress inflammatory responses in atherosclerosis." (PMID 26045945, 2015). "The synthesis and secretion of MMP-9 can be stimulated by various stimuli, including TNF-α and PDGF, during pathological processes such as atherosclerosis and inflammation." (PMID 26580653, 2015). "TNF-α and CCL2 are key mediators in chronic inflammatory processes like arthritis and atherosclerosis and the plants were selected based on their traditional use to treat these diseases or other inflammatory conditions." (PMID 25878716, 2015). "hsCRP, fibrinogen, interleukin- (IL-) 6, TNF-α, and IFN-γ showed a significant increase in patients with atherosclerosis compared to healthy controls (P < 0.05), along with a higher seroprevalence of C. pneumoniae (OR of 3.11, 95% CI: 2.88–3.36, P < 0.001)." (PMID 26346892, 2015). "Interleukin-6, TNF-α, VCAM1, ICAM1 and MCP-1 are important inflammatory cytokines that are engaged in the development of atherosclerosis, which can exacerbate it." (PMID 25661015, 2015).